TSPO (translocator protein)
Diseases named in the same sentence as TSPO in open-access papers (continued):
Sharing a sentence is not in itself a finding about the gene and the disease.
breast carcinoma (continued). "TSPO gene amplification has been witnessed in human breast cancer cell lines and metastases." (PMID 38675106, 2024). "Expression of TSPO is well recognized in different solid tumors, including breast cancer, and may be involved in the disruption in morphology and migration of mammary cancer cells." (PMID 36559209, 2022). "In addition, TSPO gene amplification has been shown in human breast cancer cell lines and metastases." (PMID 33066460, 2020). "Indeed, it has been shown that in the presence of an excess of ROS, TSPO tends to form covalent polymers in Leydig and breast cancer cells as well as in reconstituted recombinant TSPO." (PMID 27054921, 2016). "In this report, authors described the expression of TSPO in two different cell lines, MA10-Leydig and MA231-breast cancer, and showed that TSPO is expressed only in a dimeric form in MA231 and mainly in the dimeric form compared to the trimer and the monomer in MA10-Leydig cells." (PMID 27641616, 2016). "In addition, a study of 86 astrocytoma patients identified that TSPO protein expression correlated with the tumor grade and, in a small number of breast cancer samples and cell lines, TSPO protein expression correlated with malignant cancer." (PMID 25663907, 2015). "Furthermore, TSPO protein expression correlated positively with disease progression of some cancers, including oral cancers, brain cancers, colon cancers and breast cancers." (PMID 30044440, 2018). "An increase in the expression of the TSPO protein has been seen in a wide variety of malignant human cells and tissues including brain cancers, prostate cancers, colon cancers, breast cancers, oesophageal cancers, endometrial carcinomas, ovarian cancers, and hepatic carcinomas." (PMID 30044440, 2018). "In specific cases, TSPO expression correlates with the grade of the tumor malignancy and patient survival; for example, relatively high levels of TSPO density were observed in more rapidly proliferating breast cancer cells and more aggressive breast cancer phenotypes." (PMID 25663907, 2015). "However, TSPO protein overexpression was only directly determined in astrocytoma and breast cancer." (PMID 25663907, 2015). "The present study proposes to evaluate the expression of TSPO and correlate it with cell metabolism in the TME of murine mammary tumors, using [11C](R)-PK11195 and [18F]FDG PET imaging, respectively." (PMID 36559209, 2022). "In mammals, the TSPO promoter was cloned and identified from human breast cancer cells, and the binding sites of specificity protein (SP1, SP3 and SP4) positively regulate the activity of TSPO promoter." (PMID 33925909, 2021). "However, we found underexpression of EEF2 and GLRX2 proteins involved in ROS; MTX2 in MMO; USP30 in MIT; TSPO in MIT and PPM processes; BAX in FUS; and MTFR1L and MIEF1 in FIS compared to luminal A and basal-like breast cancer tumors." (PMID 35327574, 2022). "In vitro results showed IR700-6T to selectively induce apoptotic cell death in TSPO-positive but not in TSPO-negative breast cancer cells." (PMID 28218708, 2017). "The involvement of StAR in breast cancer appeared specific, as translocator protein (TSPO), a mitochondrial factor involved in steroidogenesis, was not connected (TSPO gene was amplified at 0.7% with a p-value = 0.540) with cancer deaths (data not illustrated)." (PMID 31060224, 2019). "Studies have shown that TSPO is highly expressed in estrogen-receptor (ER) negative breast tumors, representing a potential target for the development of new therapies for this subset of breast cancer." (PMID 27608010, 2016). "Finally, epigenetic regulation of TSPO expression via aberrant promotor methylation or histone modifications has been proposed, since the histone deacetylase inhibitor, TSA, induced TSPO promotor activity in human breast cancer cell lines, However, this has not been replicated in GBM so far." (PMID 33066460, 2020).
dementia (27 papers, 2012 to 2025). Loss of intellectual abilities interfering with an individual's social and occupational functions. "Regarding the imaging of inflammatory processes in AD and other pathologies linked to dementia, translocator-protein (TSPO)-tracers are used." (PMID 32848697, 2020). "Our results suggest the risk between metabolic risk factors and an increased risk for dementia might be partly modulated through inflammatory processes in the brain, and that studies assessing TSPO availability should consider taking metabolic risk factors into account." (PMID 37113066, 2023). "Selection of participants from the Translational Biomarker of Aging and Dementia (TRIAD) cohort with available translocator protein (TSPO) positron emission tomography (PET), cerebrospinal fluid (CSF) (n = 97), and plasma (n = 165)." (PMID 40289873, 2025). "The results of the meta-analysis showed that the expression level of TSPO was significantly elevated in patients with dementia, especially in the hippocampal region." (PMID 38701247, 2024). "This systematic review aims to summarize the novel available radiopharmaceuticals used for TSPO detection and explore the steps forward that scientific research has made in TSPO detection in dementia and neuroinflammation." (PMID 37189346, 2023). "The accepted studies considered the synthesis of TSPO tracers for nuclear medicine imaging in dementia and neuroinflammation." (PMID 37189346, 2023). "In the brains of patients with prodromal dementia, inflammatory cytokines and TSPO, biomarkers of neuroinflammation, are increased." (PMID 36430493, 2022). "Similar to 11C-PK11195, enhanced TSPO signals are related to impairments in cognition and memory, visuospatial and language ability, executive functioning, dementia severity, and brain atrophy." (PMID 36211392, 2022). "In this framework, TSPO-PET imaging is at present the most reliable tool to detect activated microglia in dementias and neurodegenerative disorders in general." (PMID 28475165, 2017). "However, recent studies have shown strong associations between blood-based inflammatory markers (i.e. cytokines) and central inflammation in dementia, as measured by TSPO PET." (PMID 39472664, 2025). "This hypothesis may explain the distinction in microglia states between MCI and dementia due to AD observed at follow-up, despite both of them showing increased TSPO expression when compared with healthy controls." (PMID 37520580, 2023). "Furthermore, longitudinal studies suggest that TSPO levels increase over time throughout AD progression from MCI to full-blown dementia and that astrocytes upregulate TSPO earlier in AD pathology compared to the microglia." (PMID 34573867, 2021). "Moreover, PET studies have revealed high TSPO binding in various dementias, pointing at the great potential of using TSPO as a biomarker for exploring the contribution of neuroinflammation in the pathogenesis of dementia and monitoring the progression of neurodegenerative diseases." (PMID 38139248, 2023). "Positron Emission Tomography (PET) using ligands that target the translocator protein (TSPO), which is upregulated in activated microglia, has emerged as a powerful tool for mapping neuroinflammation in various forms of dementia." (PMID 41300248, 2025). "Overall, this evidence implies a close relationship between TSPO, CD68-related microglial phagocytosis, tau-related neurodegeneration and dementia." (PMID 39540994, 2024). "A recent PET imaging study described increased TSPO expression in MCI and dementia due to AD patients, as compared with healthy controls." (PMID 37520580, 2023). "The density of TSPO could also be related to the cognitive status of patients, estimated by MMSE and/or the clinical dementia rating (CDR) scores, depending on studies." (PMID 32839410, 2020). "Below, we will review the human imaging studies aiming to characterise in vivo microglial activation in MCI and AD dementia patients, both with TSPO and non-TSPO tracers." (PMID 31396666, 2019).
dementia (continued). "Ten patients with probable or definite ALS (all right-handed, without dementia, and untreated by riluzole or other medication that might bias the binding on the TSPO), were enrolled prospectively and eight healthy controls matched for age underwent a PET study." (PMID 23300829, 2012). "Furthermore, TSPO PET imaging shows that the microglial shift, from a sensing to a reactive state, takes place at the early stage of PD and can occur even without dementia." (PMID 28387722, 2017).
brain tumor (22 papers, 2013 to 2025). "TSPO has recently gained attention as a diagnostic marker for PET imaging of brain tumors and as a potential therapeutic target due to its upregulation in GB and its correlation with features of malignancy and reduced prognosis." (PMID 37158962, 2023). "TSPO knockdown caused increased killing of U-87 MG and U-251 MG brain tumor cell lines by FluTC." (PMID 37158962, 2023). "An increase in the expression of TSPO has been observed in other malignant human cells and tissues such as brain tumors, prostate cancer, pancreatic cancer, human thyroid tumors and colon carcinoma." (PMID 40961028, 2025). "TSPO is a promising novel tracer target for positron-emission tomography (PET) imaging of brain tumors." (PMID 37697350, 2023). "The TSPO expression was found to be localized to the tumor in the F98 rat brain tumor model and was predicted to be a valuable biological target for BNCT." (PMID 36831378, 2023). "Together, these findings suggest that TSPO expression in immune cells and brain tumor cells is regulated through different IFNGR and TNFR downstream signaling pathways." (PMID 37158962, 2023). "Pharmacological microglia depletion is another valuable approach for modulation of host TSPO levels, yet to be applied in experimental brain tumor models." (PMID 35453488, 2022). "Currently ongoing in vivo and in vitro studies, both in humans and rodents, need to provide further clarity on the origin of TSPO radioligand uptake in brain tumors." (PMID 35453488, 2022). "There is significant evidence of an increase in TSPO expression in various pathologies, such as in brain tumors, brain damage, and cancer cell proliferation." (PMID 32722345, 2020). "The TSPO offers several advantages in the study of brain tumours, because its expression is increased in tumour cells but low in the normal brain and the expression can be visualized and quantified with PET imaging." (PMID 27077069, 2016). "The suitability of TSPO as molecular target for treatment of brain tumours will also be the appraised." (PMID 27077069, 2016). "For these reasons, MTX is a suitable candidate for this study and therefore it was selected as a model drug to achieve TSPO ligand-MTX conjugates, potentially useful for the treatment of TSPO-rich cancers, including brain tumors overexpressing the TSPO." (PMID 27322261, 2016). "The brain tumor has 16-fold higher TSPO expressions than its brain tissue." (PMID 36831378, 2023). "In brain tumors, TSPO is expressed by tumor cells, infiltrating immune cells and microglia." (PMID 37158962, 2023). "The role of TSPO in tumor immune resistance was experimentally determined in primary brain tumor initiating cells (BTICs) and cell lines through genetic manipulation of TSPO expression and subsequent cocultures with antigen specific cytotoxic T cells and autologous tumor-infiltrating T cells." (PMID 37158962, 2023). "In this study, we could show that the expression of TSPO is higher in brain tumor samples compared to those from epilepsy patients." (PMID 31963507, 2020). "The studies presented herein sought to extend our original observation that [18F]PBR06 may possess utility in targeting TSPO for brain tumor imaging." (PMID 26517124, 2015). "This might reflect the importance of IFNGR/TNFR signaling on TSPO expression in brain tumor cells." (PMID 37158962, 2023). "Thus, TSPO could serve as potential therapeutic tool to target brain tumors using TSPO-ligands conjugates with anti-cancer drugs." (PMID 27322261, 2016). "The earliest published evidence in support of the hypothesis that ligands targeting TSPO could be used to detect and grade human brain tumors emerged more than twenty years ago, easily predating molecular studies seeking to elucidate potential roles of TSPO function in tumorigenesis." (PMID 26517124, 2015). "All tested brain tumor cell lines and BTIC lines displayed increased immune sensitivity upon TSPO silencing." (PMID 37158962, 2023).
brain tumor (continued). "Further cell types such as activated astrocytes and endothelial cells express TSPO in the context of brain diseases and thus are likely to contribute to a certain degree to the TSPO PET signal in brain tumors." (PMID 35453488, 2022). "However, in order to clarify the source of TSPO signal at a cellular level, additional experimental methods such as immunohistochemical co-staining or innovative approaches of radiolabeled cell sorting would be helpful, and such investigations are underway in preclinical brain tumor models." (PMID 35453488, 2022). "Clinical studies agree on the suitability of quantitative FET and TSPO PET imaging for glioma grading and categorization, which ultimately may help in planning individualized strategies for brain tumor therapy." (PMID 35804911, 2022). "This rather suggests that, on balance, the interplay of tumor and host cells in generating the TSPO signal in brain tumors is not yet sufficiently understood." (PMID 35453488, 2022). "Apart from AA-PET tracers, several other radiopharmaceuticals have been developed for imaging in primary and secondary brain tumors, targeting hypoxia (18F-Fluoromisonidazole, 18F-FMISO), proliferation (3’-deoxy-3 ́-[18F]-fluorothymidine, 18F-FLT), and neuroinflammation (translocator protein, TSPO)." (PMID 33926002, 2021). "In addition, PET using the TSPO radiation ligand is not a standard imaging modality for patients with brain tumors." (PMID 36278207, 2022). "Therefore, we could conclude that FET- and TSPO-PET confer different information on pathological features based on different genetic GBM subtypes and may thus help in planning individualized strategies for brain tumor therapy in the future." (PMID 31963507, 2020). "The quantification of TSPO in PET imaging studies is challenging and brain tumours are not an exception." (PMID 27077069, 2016).
epilepsy (22 papers, 2012 to 2026). A brain disorder characterized by episodes of abnormally increased neuronal discharge resulting in transient episodes of sensory or motor neurological dysfunction, or psychic dysfunction. "By targeting the overexpression of TSPO in activated microglia and other glial cells, TSPO-PET tracers offer valuable insights into inflammatory processes associated with epilepsy." (PMID 40836311, 2025). "Together, these studies indicate that TSPO-PET can provide additional diagnostic value in MRI-negative epilepsy by revealing inflammation-associated abnormalities that are undetectable with conventional MRI." (PMID 40836311, 2025). "TSPO positron emission tomography (PET) is the most widely studied noninvasive imaging to better characterize the neuroinflammatory processes underlying epilepsy." (PMID 34976232, 2021). "Although direct evidence in epilepsy models remains limited, these mitochondrial mechanisms may underlie the association between TSPO upregulation and epilepsy pathology." (PMID 40836311, 2025). "Given its strong association with glial activation and tissue damage, TSPO serves as a reliable indicator of neuroinflammation and may represent a promising biomarker in epilepsy." (PMID 40836311, 2025). "Additionally, TSPO-PET offers insights into the pathophysiological processes underlying epilepsy, including the interplay between neuroinflammation and neuronal hyperexcitability." (PMID 40836311, 2025). "In addition, accumulation of PET ligands binding to TSPO on activated microglia has been reported in tumor-associated epilepsy." (PMID 33291423, 2020). "In the context of clinical presentation, particularly high TSPO expression in the frontal and temporal lobe raises the question of associations between pronounced regional contralateral signal elevations and respective symptoms (e.g., frontal lobe syndrome, cognitive dysfunction, epilepsy)." (PMID 39150564, 2024). "Given the established role of neurosteroids in modulating inflammation, the involvement of TSPO in neurosteroidogenesis suggests a potential link between TSPO expression and neuroinflammatory responses in epilepsy." (PMID 40836311, 2025). "In epilepsy, a consistent upregulation of TSPO has been observed in both patients and animal models." (PMID 40836311, 2025). "In the central nervous system, TSPO expression is upregulated in activated microglia, reactive astrocytes, and other glial cells during pathological states, including epilepsy." (PMID 40836311, 2025). "In the SRS model of epilepsy, TSPO levels at 14 days post-SE are predictive of SRS frequency at the onset of epilepsy." (PMID 34512540, 2021). "Several studies have reported the usefulness of TSPO PET in epilepsies, i.e., Rasmussen’s encephalitis, cerebral vasculitis, and intractable epilepsy due to encephalitis, and temporal lobe epilepsy (TLE) with hippocampal sclerosis." (PMID 33407581, 2021). "TSPO has been demonstrated as a biomarker in diseases that have a component of neuroinflammation such as epilepsy and Alzheimer’s disease." (PMID 32211931, 2020). "Among the most commonly used TSPO tracers, 18F-DPA-714 was recently shown to be able to follow TSPO expression longitudinally in a mouse model of epilepsy with hippocampal sclerosis." (PMID 32211931, 2020). "Studies have thus used PET molecular imaging to investigate TSPO levels and neuroinflammation in epilepsy." (PMID 30626103, 2019). "Data gained by F-18-GE180 PET in a rat model of epileptogenesis demonstrates the suitability of TSPO PET to reveal the time course of neuroinflammation during epilepsy development and to identify brain regions involved in this process." (PMID 29326952, 2017). "In addition, we examine correlations between TSPO SUVr and inflammatory factors to identify potential peripheral blood inflammatory predictors of post-COVID-19 active epilepsy." (PMID 41616056, 2026).